SERPINH1 (serpin family H member 1)
Diseases named in the same sentence as SERPINH1 in open-access papers (continued):
Sharing a sentence is not in itself a finding about the gene and the disease.
paraganglioma (2 papers, 2021 to 2022). A benign or malignant neoplasm arising from paraganglia located along the sympathetic or parasympathetic nerves. "Also, SERPINH1 expression showed strong association with immunoregulators and immune checkpoint markers in testicular germ cell tumors, brain lower grade glioma (LGG), pheochromocytoma and paraganglioma." (PMID 35058967, 2021).
prion disease (2 papers, 2019 to 2022). A transmissible disease that is caused by a protein that is able to induce abnormal folding of normal cellular proteins, leading to characteristic spongiform brain changes, which are associated with neuronal loss without an inflammatory response. "Some DEGs are found to be related to prion disease, including Ywhag, Mt2, Serpinh1 and Cst3." (PMID 31767948, 2019). "Our analysis revealed that, besides the already observed upregulation of SERPINA3 in patients with prion disease and AD, SERPINB1, SERPINB6, SERPING1, SERPINH1, and SERPINI1 were dysregulated in sCJD individuals compared to controls, while only SERPINB1 was upregulated in AD patients." (PMID 35416570, 2022).
prostate adenocarcinoma (2 papers, 2022 to 2025). "Meanwhile, the underexpression of SERPINH1 was found only in PRAD (prostate adenocarcinoma)." (PMID 36105106, 2022).
breast invasive carcinoma (1 paper, 2021). "In addition, SERPINH1 expression was related to immune cell infiltration in multiple cancers, particularly in breast invasive carcinoma, LGG, and liver hepatocellular carcinoma." (PMID 35058967, 2021).
cholesteatoma (1 paper, 2015). A pathologic process characterized by the proliferation of keratinizing squamous epithelium resulting in the accumulation of keratin and cells in the middle ear and/or mastoid. "Elevated SERPINH1 in cholesteatoma-involved ossicles suggests either increased bone remodeling or repair of the affected bones." (PMID 26608071, 2015).
chondrosarcoma (1 paper, 2024). A malignant cartilaginous matrix-producing mesenchymal neoplasm arising from the bone and soft tissue. "HSP47, a SERPINH1 gene encoded protein was reported as RA-related antigen protein from a human chondrosarcoma-derived chondrocytic cell line." (PMID 39666600, 2024).
coronary artery disease (1 paper, 2022). "These genes included Cdh13 and Lpl from Cluster 1; Nfia, Col4a1 and Serpinh1 from Cluster 2; Arhgef12, Col4a2, Scarb1 and Cst3 from Cluster 3; Pecam1 and Aldh2 from Cluster 4, providing plausible molecular basis for the inextricable causal link between age and coronary artery disease." (PMID 35615560, 2022).
Fibroadenoma (1 paper, 2020). A benign tumor of the breast characterized by the presence of stromal and epithelial elements. "For fibroadenoma tissues, compared with both fibroadenoma-adjacent and normal tissues, there were six up-regulated (ANXA6, VCP, SERPINH1, galactosidase alpha, NNT, and MMP11) and 38 down-regulated (KRT10, KRT1, ALDH1A1, ECM1, and others) proteins in fibroadenoma." (PMID 33194682, 2020).
hepatitis C (1 paper, 2024). "BMS-986263 is a lipid nanoparticle delivering small interfering RNA targeting SERPINH1 mRNA, and it has shown promising safety and significant improvement in fibrosis status in a phase II trial for the treatment of advanced fibrosis in hepatitis C patients." (PMID 39430252, 2024).
Hypertension (1 paper, 2023). The presence of chronic increased pressure in the systemic arterial system. "Other proteins such as Serine peptidase inhibitor 1 (Serpinh1) and Prohibitin are enriched with aging and hypertension." (PMID 37092014, 2023).
hypoxic-ischemic encephalopathy (1 paper, 2025). "SERPINH1 encodes HSP47, a collagen-specific molecular chaperone that contributes to extracellular matrix stabilization and has been associated with protective responses in hypoxic-ischemic encephalopathy." (PMID 41152969, 2025).
liver cancer (1 paper, 2024). An epithelial or non-epithelial malignant neoplasm that arises from the liver. "Taking liver cancer as an example, SERPINH1 was identified as an effective biomarker and drug target applicable to both tumors and NATs." (PMID 39430252, 2024). "In addition, this study has informed that BMS-986263, an inhibitor targeting SERPINH1, may inhibit the occurrence and development of liver cancer." (PMID 39430252, 2024).
Osteogenesis (1 paper, 2021). "Mutation of SERPINH1 was associated with a severe phenotype of Osteogenesis Imperfecta, in which the secreted type I collagen structure was compromised and became sensitive to protease activity." (PMID 35118144, 2021).
Osteopenia (1 paper, 2024). Osteopenia is a term to define bone density that is not normal but also not as low as osteoporosis. "Furthermore, mutation in the SERPINH1 gene, responsible for the maturation of type 1 collagen, has been identified as a novel OI gene linked to the manifestation of severe osteopenia and dentinopaenia in two litters of Dachshunds." (PMID 39559541, 2024).
parasite (1 paper, 2018). "Our thorough literature review showed that SERPINH1 has not been recognised as an upregulated gene in response to any other stressors in fish, although in mammals it is also associated with fibrosis in response to parasite infections." (PMID 30326831, 2018).
prostate carcinoma (1 paper, 2022). A carcinoma that arises from epithelial cells of the prostate gland. "Knockdown of CNDP2 and SERPINH1 expression inhibited the proliferation of prostate cancer cell lines." (PMID 36700224, 2022). "The qPCR results revealed that the expression of CNDP2 was high in four PC cell lines (LNCap, PC-3, C4-2, and 22RV-1), and the expression of SERPINH1 was high in immortalized prostate cell lines like RWPE-1 compared with four prostate cancer cell lines." (PMID 36700224, 2022). "According to our in vitro experiments, we found that CNDP2 and SERPINH1 promote tumor invasion and cell proliferation and reduce cell apoptosis in prostate cancer." (PMID 36700224, 2022).
scoliosis (1 paper, 2025). A congenital or acquired spinal deformity characterized by lateral curvature of the spine. "SERPINH1 shared the same variant with CX3CR1 on CD14− CD16− which could increase the risk of scoliosis." (PMID 40177401, 2025). "In our MR analysis, we noted that the increased expression of CX3CR1 on CD14− CD16−, which shared the same variant with SERPINH1, and CCR2 on CD14− CD16−, which shared the same variant with FSD1L, was associated with an elevated risk of scoliosis." (PMID 40177401, 2025). "Controlling the balance between CX3CR1 and SERPINH1 may be beneficial for intervention in scoliosis." (PMID 40177401, 2025). "We hypothesized that CX3CR1 may inhibit the function of SERPINH1, which could result in immune disorders and, ultimately, scoliosis." (PMID 40177401, 2025).
small cell lung carcinoma (1 paper, 2022). Small cell lung cancer (SCLC) is a highly aggressive malignant neoplasm, accounting for 10-15% of lung cancer cases, characterized byrapid growth, and early metastasis. "However, high expression of SERPINH1 was mainly correlated with DNA replication, ECM–receptor interaction, homologous recombination, IL-17 signaling pathway, and small cell lung cancer." (PMID 36105106, 2022).
tumor (92 papers, 2006 to 2026). "Based on previous studies, SERPINH1 has been implicated in tumor progression through the regulation of immune functions and cell death processes, such as apoptosis and autophagy." (PMID 40705756, 2025). "SERPINH1 is abnormally expressed in multiple cancers and is associated with tumor progression, making it a potential prognostic marker." (PMID 40530702, 2025). "In recent years, SERPINH1 has emerged as a key player in tumor biology, with its dysregulated expression implicated in the malignant progression of various cancers." (PMID 40705756, 2025). "Higher abundance of SERPINH1 in tumor tissues is associated with increased activity in pathways related to platelet, neutrophil, and epithelial-mesenchymal transition." (PMID 39430252, 2024). "Patients with elevated SERPINH1 in both tumor and NATs (T2-NAT2) exhibited the highest risk of recurrence, with a 5-year DFS rate reaching 78.95%." (PMID 39430252, 2024). "Our results suggest that SERPINH1 expression affects the prognosis of patients with pan-cancer and is significantly associated with tumor immune invasion." (PMID 36105106, 2022). "To determine the role of SERPINH1 in tumor progression, we evaluated the association of the SERPINH1 expression with five MMR genes mutation levels." (PMID 35058967, 2021). "Tumor cell overexpressed SERPINH1 encodes the endoplasmic reticulum resident heat shock protein 47 (Hsp47), a molecular chaperone that fosters collagen type I production and export through the secretory pathway during epithelial-mesenchymal transition." (PMID 33937274, 2021). "Pearson correlation analysis was applied to evaluate the role of SERPINH1 expression in tumor mutation burden (TMB), microsatellite instability (MSI), mismatch repair (MMR), DNA methyltransferase, and common immunoregulators." (PMID 35058967, 2021). "Furthermore, GSEA analysis revealed significant downregulation of representative pathways associated with high SERPINH1 expression—such as collagen metabolism, angiogenesis, tumor stemness, and alternative splicing—in the Col003-treated group." (PMID 39430252, 2024). "Emerging studies demonstrate that SERPINH1 is closely associated with cancer development and may be referred to as a potential biomarker of tumours." (PMID 35876041, 2022). "In addition, high expression of SERPINH1 was positively associated with tumor stage and poor prognosis." (PMID 36105106, 2022). "Subsequently, two independent sets (n = 532 and 105) verified the high level of SERPINH1 in ccRCC tissues and its association with reduced overall survival and disease‐free survival in all tumour‐node‐metastasis stages and patients with von Hippel–Lindau wild‐type (VHL‐WT)." (PMID 29239102, 2018). "These analyses revealeda significant upregulation of ER chaperone mRNA expression in aHGGrelative to aLGG and aNNB that was associated with tumor aggressiveness and patientsurvival for HSPA5, HSP90B1, P4HB, and SERPINH1." (PMID 41287960, 2026). "This highlights a novel mechanism by which SERPINH1 contributes to tumor biology and underscores its potential as a therapeutic target." (PMID 40705756, 2025). "In vitro co-culture experiments further demonstrated that GBM cells can recruit and activate astrocytes at the tumor periphery, inducing overexpression of SERPINH1 and COL5A1." (PMID 40530702, 2025). "Specifically, ECM-associated genes such as SERPINH1, SPARCL1, and HYAL1 have been implicated in modulating immune cell behavior within the tumor milieu." (PMID 40426943, 2025). "Through analysis of TCGA-CESC datasets, we identified that high SERPINH1 expression is significantly correlated with poor prognosis and contributes to tumor progression by promoting cell proliferation, invasion, and metastatic phenotypes." (PMID 40705756, 2025). "Among them, the subgroup with high expression of SERPINH1 in both tumor and NAT corresponds to patients who all relapsed within 5 years." (PMID 39430252, 2024).
tumor (continued). "To further validate the predictive efficacy of SERPINH1 for recurrence, we enrolled two independent validation cohorts consisting of tumor and paired NAT samples and validated them using immunohistochemistry (IHC)." (PMID 39430252, 2024). "The IHC staining of SERPINH1 is mainly localized in the tumor stroma, with clear distinctions in staining intensity." (PMID 39430252, 2024). "Compared to the NATs, the IHC score of SERPINH1 was significantly higher in the tumor tissues (T-average: 2.29; N-average: 1.38; P<0.001)." (PMID 39430252, 2024). "SERPINH1 has been identified as a promising biomarker and drug target for predicting postoperative recurrence in both the tumor and its NAT." (PMID 39430252, 2024). "In human pan-cancer, SERPINH1 has been found to be a crucial prognostic biomarker that correlates to tumor immunity." (PMID 38055382, 2023). "In this study, the application of immunofluorescence‐based IHC confirmed in a second cohort the dramatic increase in Hsp47/SERPINH1 abundance identified by MS in the tumor stromal microenvironment of a first cohort of LSCC patients." (PMID 36228107, 2023). "The elevated mRNA expression of SERPINH1 in tumor tissues of GC indicates trouble in collagen maturation." (PMID 36596829, 2023). "The results indicated that the inhibition of SERPINH1 obviously decreased the dissemination of abdominal tumour nodules as compared to controls." (PMID 35876041, 2022). "We explored the expression of SERPINH1 in KIRC tumor microenvironment cells and compared the SERPINH1 expression across cell types." (PMID 36105106, 2022). "The results revealed that SERPINH1 expression had a positive correlation with tumor stage in most of the cancers." (PMID 36105106, 2022). "We also found that SERPINH1 expression has a positive correlation with tumor stage in pan-cancer according to our research." (PMID 36105106, 2022). "The high expression of SERPINH1 in some tumors is related to cell proliferation, tumor stage, pathological grade, and poor prognosis." (PMID 36105106, 2022). "Among them, SERPINH1, a molecular chaperone which has been reported to be closely related to tumor proliferation and metastasis was highly expressed in NPC tissues." (PMID 35227262, 2022). "Particularly in ACC and TGCT, the expression of SERPINH1 increased with the progression of tumor stage." (PMID 36105106, 2022). "The expression of SERPINH1 was significantly higher in tumor cells and endothelial cells than in immune cells (p < 0.05)." (PMID 36105106, 2022). "In order to clarify the relationship between SERPINH1 expression and early and late stages of tumor, we combined stages I–II as early and III–IV as late for analysis." (PMID 36105106, 2022). "To better realize the relationship between the expression of SERPINH1 and tumor stages, we further analyzed SERPINH1 expression in diverse World Health Organization tumor stages." (PMID 36105106, 2022). "We believe that SERPINH1 is likely to be a new target for tumor therapy, so it is very urgent to carry out pan-cancer research on SERPINH1." (PMID 36105106, 2022). "SERPINH1 is related to tumor immunity and can change the composition of immune cells by inducing the tumor microenvironment, but its mechanism is still unclear and needs further study." (PMID 36105106, 2022). "For the first time, single-cell transcriptome sequencing data were used to assess the expression of SERPINH1 in different cells of the tumor microenvironment." (PMID 36105106, 2022). "SERPINH1 staining was higher in tumor samples than in normal tissue, which was consistent with the result of survival analysis, indicating that high expression of SERPINH1 is a risk factor in COAD, HNSC, KIRP, and CESC." (PMID 35058967, 2021). "High-SERPINH1 patients also showed more depth of tumor invasion (χ2 = 5.979, P = 0.014) and more advanced TNM stage (χ2 = 9.854, P = 0.002) than the low-SERPINH1 ones." (PMID 34215253, 2021).
tumor (continued). "High-SERPINH1 patients showed more depth of tumor invasion and more advanced TNM stage than the low-SERPINH1 ones." (PMID 34215253, 2021). "Spearman’s correlation test was used to analysis SERPINH1 expression in tumor immune infiltration and infiltrating immune cells via the Tumor Immune Evaluation Resource database." (PMID 35058967, 2021). "To test if SERPINH1 expression is regulated by tumor‐specific factors, we performed co‐culture experiments." (PMID 33377644, 2020). "In vivo knockout of SERPINH1 has been shown to significantly reduce tumor growth." (PMID 40530702, 2025). "Additionally, SERPINH1 regulates tumor cell death mechanisms, including autophagy and apoptosis, further underscoring its multifaceted role in cancer biology." (PMID 40705756, 2025). "Given the critical role of glycan modification in tumor progression—including cell signaling, invasion, angiogenesis, and metastasis, this finding provides a novel mechanistic perspective on oncogenic activity of SERPINH1." (PMID 40705756, 2025). "This paradigm-shifting discovery may inform the development of innovative therapeutic strategies targeting SERPINH1 or its downstream cell death effectors to suppress tumor growth and metastasis." (PMID 40705756, 2025). "Further validation using Gene Set Enrichment Analysis (GSEA) demonstrated that SERPINH1 positively correlated genes were significantly enriched in tumor invasion pathways, whereas its negatively correlated genes were prominently enriched in metastasis suppression pathways." (PMID 40705756, 2025). "Targeting SERPINH1 can effectively delay tumor occurrence and progression." (PMID 39430252, 2024). "Consistent with the high AFP abnormality in the high SERPINH1 expression group in tumors, the high SERPINH1 expression group in tumors also showed enrichment of tumor stemness pathways, along with abnormal activity in unfavorable pathways such as alternative splicing and DNA replication." (PMID 39430252, 2024). "Remarkably, several of these target genes were down-regulated following miR-Combo treatment, and have been shown to be involved in GBM progression (RAP2A), angiogenesis (SPON2), migration (CXCR4), and are associated with an increase in tumor grade (IGF2BP3, SERPINH1)." (PMID 37749143, 2023). "However, human pan-cancer evidence regarding the potential effects of the SERPINH1 gene in various tumor types is incompletely understood." (PMID 36105106, 2022). "Moreover, Immune infiltration analysis revealed that each component in the ceRNA network (H19/miR-378a-5p/SERPINH1) was significantly correlated with the infiltration abundances of diverse tumor-infiltrating immune cells." (PMID 36104825, 2022). "A previous study showed that SERPINH1 could promote the maturation of procollagen, which is closely related to tumor metastasis." (PMID 36105106, 2022). "It suggested that SERPINH1 was closely related to this tumor progression." (PMID 36105106, 2022). "SERPINH1 is involved in tumour progression, diagnosis and therapy." (PMID 35876041, 2022). "Moreover, this study totally explored the correlation of SERPINH1 with immunoregulators, immune checkpoints, and tumor-infiltrating immune cells in 33 tumor microenviroments." (PMID 35058967, 2021). "Results indicate that SERPINH1 may regulate the tumor progress by MMR-mediated DNA repair and DNA methylation." (PMID 35058967, 2021). "Since there may be non-tumor death factors during follow-up, we further explored the relationship between SERPINH1 expression and patients’ DSS." (PMID 35058967, 2021). "Moreover, tumor tissues obtained from patients with high-risk scores tended to express high level of prognostic genes (AGT, SERPINH1 and MMP7)." (PMID 34215253, 2021). "Finally, we analyzed the anti-tumor effects of Col003, a small molecule inhibitor of the SERPINH1 protein." (PMID 32091407, 2020).